PCNA (proliferating cell nuclear antigen)
Diseases named in the same sentence as PCNA in open-access papers (continued):
Sharing a sentence is not in itself a finding about the gene and the disease.
tumor (continued). "In conclusion, the cis effect of PCNA amp elevates PCNA protein expression, inducing cell proliferation and leading to an increase in tumor size in the intestinal-type." (PMID 39762212, 2025). "In HCC, molecular indicators of prognosis include the proliferating cell nuclear antigen (PCNA), and matrix metalloproteinases (MMPs) enzymes have been associated with tumor progression, invasion, and metastasis, which can contribute to a worse prognosis." (PMID 40740599, 2025). "The results revealed a significant correlation between clinical indicators (including PCNA expression and tumor incidence) and the intratumoral microbiota in HNSCC." (PMID 41395468, 2025). "Through further immunohistochemical analysis, the protein levels of PCNA and Ki67 in the tumor tissues were lower in the combination group than in the fruquintinib single-agent group." (PMID 39735667, 2025). "Jervine treatment significantly inhibited tumor growth, reduced Ki67 and PCNA positive cell numbers and restored E-CAD and N-CAD expression." (PMID 40740234, 2025). "Lupeol markedly reduced the regions strongly stained for PCNA and Ki-67 in tumor tissues relative to NT and solvent control groups." (PMID 40417209, 2025). "Both PGPs and PGPs-NE markedly improved these parameters, with PGPs-NE showing greater effectiveness in reducing tumor weight, restoring antioxidant levels, and inhibiting the expression of PCNA, MMP-9, and IL-6." (PMID 41307829, 2025). "In several tumors, upregulation of PCNA waslinked with differences in tumor-infiltrating lymphocytes, and specificimmune-inhibitors, and chemokines." (PMID 40657100, 2025). "Cytosolic PCNA also promotes neutrophil survival, fostering chronic inflammation that can sustain tumor growth." (PMID 41170373, 2025). "A prime example is the development of novel PCNA inhibitors, which aim to disrupt DNA replication and repair, the key processes essential for tumor proliferation." (PMID 41170373, 2025). "The results of H&E and IHC showed that the positive rate of MCM3 and PCNA was markedly reduced in shMCM3 group tumor samples compared with shNC group." (PMID 39991578, 2025). "There was a notable positive correlation between the expression of PLK1 and the expression of proliferating cell nuclear antigen (PCNA) (R = 0.68) in tumor tissue (right)." (PMID 40355412, 2025). "Subsequent detection of PCNA levels in tumor tissues revealed decreased protein and mRNA expression in the shMETTL1 group, as indicated by IHC, western blotting, and qRT-PCR analyses." (PMID 39870616, 2025). "Ki67 and PCNA are established markers of cell proliferation and widely used to evaluate tumor cell growth." (PMID 40740234, 2025). "At a dosage of 30 mg/kg, it significantly reduced tumor load and affected PCNA, TUNEL, p-STAT3, and cyclin D1 in vivo." (PMID 38276618, 2024). "And knockout of SRC‐1 in mice reduced diethylnitrosamine/CCl4‐induced tumour formation in the liver and the expression of c‐Myc and PCNA in liver tumours." (PMID 38506084, 2024). "Immunocompetent mice administered with C‐176 and cisplatin exhibited the slowest tumour growth and lowest PCNA expression levels." (PMID 39183480, 2024). "In this present study, we found that Ecn decreased the levels of PCNA and c-Myc, inhibited cell viability and clone formation in vitro, and restrained xenograft tumor growth of BC cells in vivo." (PMID 37692489, 2024). "Knockdown of RNH1 leads to upregulation of PCNA in tumor tissues, representing an increased proliferative capacity of cells." (PMID 38783241, 2024). "The PCNA immunostaining revealed that Capan-1 cells bearing PGR shRNA showed inhibition of PDAC tumor progression." (PMID 38424455, 2024). "The histological analysis showed the effects of co-administering PDT with oxaliplatin and gemcitabine on tumor necrosis, cell apoptosis, proliferating cell nuclear antigen labeling index (PCNA LI), and percentage of the VEGF-immunopositive area (PVIA) (%)." (PMID 39598543, 2024).
tumor (continued). "In a hamster model, α-mangostin (100 mg/kg) significantly reduced tumor size, bile duct proliferation, and the expression of proliferating cell nuclear antigen (PCNA) in tumor tissue." (PMID 39595559, 2024). "We measured levels of the Ki-67 and proliferating cell nuclear antigen (PCNA) in tumor tissue by immunohistochemistry assay." (PMID 38424632, 2024). "The results of our study revealed a significant relationship between the immunohistochemical expression of GR and tumour histological grade, depth of invasion, regional lymph node involvement, staging, and PCNA immunohistochemical expression." (PMID 38256170, 2024). "Further, the knockdown of RARγ in A2780 xenografts resulted in decreased tumor weight and volume along with reduced expression of RARγ, Ki-67, and PCNA." (PMID 39077471, 2024). "Hematoxylin and eosin (H&E) and proliferating cell nuclear antigen (PCNA) staining revealed that tumors treated with HY-oAd+9-ING-41 were nearly devoid of PCNA-positive cell population (***p < 0.001) and that most of the tumor tissues were necrotic." (PMID 38812516, 2024). "Decreased Ki-67 expressions and PCNA expressions in CM-injected tumor tissues also suggested attenuated tumor proliferation." (PMID 38360722, 2024). "Correspondently, our results showed that CFZ treatment remarkably reduced Ki67 and PCNA expressions in tumor tissues of mouse xenograft model of HCC, compared with the control treatment." (PMID 38591121, 2024). "It was observed that dietary methionine dramatically expedited heterotopic ESCC tumor growth in a dose-dependent manner, accompanied by enhanced intratumoral expression of cyclin B1 and PCNA." (PMID 38570607, 2024). "Histopathological changes in the intestines were assessed using H&E staining, and the expression of the tumor proliferation marker, proliferating cell nuclear antigen (PCNA), was assessed using immunohistochemical staining." (PMID 39096436, 2024). "PCNA is found to be upregulated in proliferative tumor cells and a marker of sensitivity to chemotherapy." (PMID 38245530, 2024). "In vivo studies demonstrated that the inhibition of M2 polarization reduces tumor burden and invasiveness (proliferating cell nuclear antigen (PCNA) and VEGF ratio) and increases HCC cell apoptosis." (PMID 38397187, 2024). "Immunohistochemical analysis revealed that the expression of HIST3H2A and PCNA in LV-HIST3H2A tumor tissues was significantly lower than that in the control group." (PMID 38684944, 2024). "The proliferative potential of tumor masses was assessed by analyzing the expression of PCNA through Western blot and IHC." (PMID 39125971, 2024). "Based on the establishment of xenograft models in BALB/c nude mice, we discovered that PPCKM reduced tumor volume and weight, inhibited proliferating cell nuclear antigen (PCNA) and Ki67 expression, as well as promoted apoptosis by targeting the tumor site." (PMID 39649540, 2024). "The PCNA analysis revealed that the PEG-MnMOF@PTX group exhibited the most potent inhibition of tumor cell proliferation, highlighting the combination on combating tumors." (PMID 38715912, 2024). "Meanwhile, tumor proliferation was assessed in vivo by analyzing the expression of PCNA and Ki-67 in subcutaneous tumors via IHC." (PMID 39668819, 2024). "The results indicated that the expression levels of ki67 and PCNA were reduced within the tumor tissues that overexpressed hsa_circ_0050386." (PMID 38216996, 2024). "Immunohistochemical analysis was conducted to determine the expression of CD31 and PCNA in tumor tissues, while apoptosis was assessed using the TUNEL method." (PMID 38751791, 2024). "This was surprising given the conflicting nature between PCNA+ TAM association with poor prognosis and the anti-tumour immune response that M1 macrophages elicit." (PMID 39205238, 2024).
tumor (continued). "CDKN1A and PCNA inhibit the transition from the G1 to the S phase of the cell cycle, thus blocking cancer cell division and tumor growth." (PMID 39339270, 2024). "Broad nuclear expression of PCNA was observed in the tumor-bearing mice compared to the expression in the lung normal parenchyma of healthy skin-treated mice." (PMID 38698774, 2024). "NUTF2 expression was found to be highly correlated with MKI67 and PCNA in 27 tumor types including ACC, BLCA, and BRCA (P < 0.05)." (PMID 38402311, 2024). "We performed subcutaneously cancer cell injection in nude mice, revealing that PCIF1 silencing significantly inhibits tumor growth, corroborated by reduced staining of the proliferation index marker PCNA." (PMID 39422663, 2024). "The expression of PCNA in the tumor tissue of the colon in the AOM/DSS group was significantly higher than that in the Control and PZH groups (#P < 0.05)." (PMID 39020410, 2024). "Specifically, CBD administration in animal models resulted in a reduction in tumor cell division by downregulating the expression of PCNA, highlighting its potential clinical applications." (PMID 39850601, 2024). "In vivo, ADFP enhanced tumor formation in nude mice, with elevated levels of p-Akt/Akt, Ki67, and PCNA." (PMID 39684299, 2024). "The PCNA scores for the tumor tissue were significantly different (p < 0.001) than those of the control mammary tissue." (PMID 39734347, 2024). "IHC was used to assess the expression of PCNA, BCL-2, and cleaved caspase-3 in tumor tissues, revealing decreased expression of PCNA and BCL-2 and increased expression of cleaved caspase-3." (PMID 38334883, 2024). "Instead, overexpression of USP27X‐AS1 increased tumour burden, PCNA and liver metastasis nodules (each group n = 7)." (PMID 38279869, 2024). "The subcutaneous tumor tissues of the sh-ME2-R67K group exhibited considerably lower expression levels of Ki67 and PCNA than did the tumor tissues of the sh-ME2-WT group." (PMID 39528487, 2024). "This was evidenced by smaller tumor volumes and lighter tumor weights, as well as decreased expressions of Ki-67 and PCNA, demonstrating the in vivo antitumor effect of PPIB." (PMID 38360722, 2024). "Through immunohistochemical assay, elevated levels of BLM, Ki-67, and PCNA were observed in the tumor tissues with circ_0001671 overexpression when compared to those in the control group." (PMID 38806577, 2024). "Immunohistochemical analysis showed that the expression level of ki67 and PCNA, which are closely related to tumor proliferation, were significantly lower in the siRNA3 group than in siNC." (PMID 38558328, 2024). "Immunohistochemical analysis of Ki-67 and PCNA showed that JB treatment had a significant inhibitory effect on tumor cell proliferation." (PMID 39440048, 2024). "In the tumor area, Probio-M9 treatment substantially suppressed the increase in proliferating cell nuclear antigen- and Ki67-positive cells in the AOM/DSS model." (PMID 38540144, 2024). "High mRNA expression of CDK1, PCNA, EZH2, BUB1, and CXCR4 in tumor was significantly associated with lower RFS." (PMID 38831458, 2024). "The decreases in Ki67 and PCNA expression and increase in cleaved caspase-3 expression in the Nur77-overexpressing xenografts further supported the tumor inhibitory effect of Nur77." (PMID 38789431, 2024). "(G) Representative images of hematoxylin and eosin (H&E) staining (upper) and immunohistochemical staining for PCNA on paraffin sections of tumor tissues (bottom)." (PMID 38536720, 2024). "In vivo experiments in the HCT-116 subcutaneous tumor-bearing model also demonstrated a significant decrease in the expression of Ki-67 and PCNA following treatment with esculetin." (PMID 39346560, 2024).
tumor (continued). "Remarkably, PCNA overexpression effectively rescued the tumor-inhibitory effects induced by EIF3B knockdown, resulting in heightened proliferation and migration, alongside the inhibition of apoptosis." (PMID 38687509, 2024). "And the Ki67 and PCNA percentage area of tumor cells was relatively increased in NR4A3 knockout or knockdown group when compared with their control group." (PMID 39664575, 2024). "IHC analysis revealed a decrease in the expression levels of the proliferation markers Ki-67 and PCNA in the tumor tissues following treatments with Spautin-1 and cisplatin." (PMID 39218913, 2024). "The proliferation markers Ki67 and PCNA, indicative of tumor proliferation, were significantly reduced in the combination treatment group, while the cell proliferation inhibitory protein p21 was substantially increased." (PMID 38273343, 2024). "The results of our study revealed a significant relationship between the immunohistochemical expression of Grx2 and tumor histological grade, depth of invasion, regional lymph node involvement, angioinvasion, staging, and PCNA immunohistochemical expression." (PMID 38256132, 2024). "The expression of NR4A3 was negatively correlated with Ki67 and PCNA in TCGA dataset as well as in NR4A3-overexpressing tissues collected from nude mice with tumor xenografts." (PMID 39664575, 2024). "PCNA is expressed in the nuclei of normal proliferating cells and tumor cells, involved in DNA replication, and is an important protein for cell proliferation." (PMID 38580754, 2024). "PCNA exists in normal proliferating cells and tumor cells, and IHC staining can show significant positive results when tumor tissues are formed." (PMID 37234705, 2023). "MβCD significantly mitigated the overexpression of PLPP2-induced excessive proliferation, characterized by high-positive staining of Ki-67 and PCNA in tumor tissues." (PMID 37996944, 2023). "Expression levels of MCM2 and PCNA in xenograft tumor tissues were lower in the shGBAP1-2 group than that in the NC group." (PMID 37407932, 2023). "The PCNA protein is essential for tumor cell proliferation and participates in a variety of processes of DNA metabolism." (PMID 36626251, 2023). "In the present study, there was also a marked increase in PCNA-positive tumor cells, as well as in the gene expression levels of VEGF in the H group." (PMID 37175975, 2023). "Based on our observations, we propose that PCNA serves as a docking site for replication factors regulated by USP37, which helps the cells to manage replication stress associated with the tumor microenvironment." (PMID 37118828, 2023). "The study also found that direct injection of miR-19a into a xenograft tumor model led to accelerated tumor growth and increased proliferating cell nuclear antigen accumulation." (PMID 37629689, 2023). "The Western blotting results showed that the expression of p-EGFR and PCNA (proliferating cell nuclear antigen) in the subcutaneous tumor tissues was significantly decreased in the acacetin group (50 mg/kg) compared with the control group (p < 0.05)." (PMID 37266143, 2023). "Meanwhile, the Ki67 (cell proliferation markers, proliferating cell nuclear antigen) expression was decreased in DW14761‐treated tumor tissues." (PMID 36999124, 2023). "Our study found six genes (PCNA, CDC6, CDC7, CDT1, CDK2, and RBBP8) that were most significantly linked with expression levels of key genes and tumor progression." (PMID 37656243, 2023). "PCNA is an essential protein in DNA replication and repair and functions by anchoring DNA polymerases and DNA editing enzymes, inhibiting tumor cell proliferation." (PMID 36820067, 2023). "PCNA-positive cells showed a slightly elevated in the non-tumor areas of the CDAA-HF-T(-) group compared to controls." (PMID 37535625, 2023). "Cell proliferation in tumor tissues was assessed by analyzing the percentage of Ki-67 and proliferating cell nuclear antigen (PCNA) positivity." (PMID 37996944, 2023).
tumor (continued). "The high expression of Gpx-2 was correlated with the histological grade of the tumour (p < 0.001), PCNA immunohistochemical expression (p < 0.001), depth of invasion (p = 0.001) and angioinvasion (p < 0.001)." (PMID 37834097, 2023). "Consistently, PCNA staining is highest for tumor overexpressing MAX, and the opposite is true for MAX knockdown (bottom)." (PMID 37347224, 2023). "Compared with DMSO treatment, ar-turmerone treatment also downregulated the proliferation markers KI67 and proliferating cell nuclear antigen (PCNA) in tumor tissues." (PMID 37768200, 2023). "The immunohistochemical analysis of tumor cell proliferation revealed up to 50% PCNA-positive cells in the rEP, BML, and Sham groups (rEP 3.6 ± 0.2; BLM 3.4 ± 0.3; and Sham 3.3 ± 0.3)." (PMID 36900388, 2023). "The results of IHC indicated that tumor generated from Lv-miR-6836 cells had higher PCNA and lower DLG2 expression." (PMID 37416779, 2023). "Then, the tumor was dissected and IHC was performed, the results showed that the volume of cell nuclei in controls significantly increased, and PCNA was expressed in most cells in controls and was significantly higher than that in FEN1-shRNA group." (PMID 37185662, 2023). "PCNA inhibitors are currently being investigated as anti-cancer therapies due to the preferential inhibitory effects on proliferating tumor cells that are actively engaged in DNA replication." (PMID 37486931, 2023). "The high expression of Notch4 was clearly correlated with the histological grade of the tumour (p < 0.001), PCNA immunohistochemical expression (p < 0.001), depth of invasion (p < 0.001) and angioinvasion (p < 0.001)." (PMID 37108670, 2023). "And vice versa, the overexpression of NDFIP1 resulted in smaller tumor size and weight, lower level of PCNA and Ki-67 in vivo." (PMID 36929005, 2023). "In contrast, ASPA knockdown resulted in increased tumor weights and up-regulated expression of PCNA, cyclin D1, N-cadherin, and MMP9 (P < 0.05 or P < 0.01), concomitant with the inhibition of E-cadherin expression (P < 0.01)." (PMID 37271807, 2023). "qRT-PCR demonstrated that the mRNA expression of PCNA, Vimentin and Twist was downregulated in tumor tissue samples compared with that in the lv-NC group." (PMID 36718644, 2023). "Oral administration of CAR significantly suppressed tumor growth and immunohistochemical analyses showed low levels of proliferative proteins, including PCNA (proliferating cell nuclear antigen) and Ki-67." (PMID 37373500, 2023). "We confirmed that USP44 deletion significantly promoted the proliferation of tumor cells through immunofluorescence of proliferating cell nuclear antigen (PCNA) in tumor samples." (PMID 38097536, 2023). "The efficacy and toxicity were analyzed by measuring the respective tumor sizes and mouse weights accompanied by histological analysis of the protein levels of proliferating cell nuclear antigen (Pcna), glucose transporter 1 (Glut-1), and CD3." (PMID 36672190, 2023). "The expression of Ki67 and proliferating cell nuclear antigen (PCNA) in tumor tissues was markedly decreased by ZY0511, further demonstrating the proliferation inhibitory potency of ZY0511 in vivo." (PMID 37250145, 2023). "PCNA plays a significant role in promoting the cancerous phenotype by actively participating in crucial processes that are essential for the survival of tumor cells." (PMID 37686697, 2023). "The results showed a reduced tumor burden in Juglone‐treated tumor and immunohistochemistry showed a reduction in PCNA expression of Juglone‐treated tumor, indicating that Pin1 inhibition inhibits tumor proliferation in vivo." (PMID 36684109, 2023). "The proportion of PCNA- and Ki-67-positive tumor cells in the control group significantly increased compared with that in the Arte, 5-FU and 5-FU combination treatment groups." (PMID 37498338, 2023).